TLR4 (toll like receptor 4)
Diseases named in the same sentence as TLR4 in open-access papers (continued):
Sharing a sentence is not in itself a finding about the gene and the disease.
immune disorders (continued). "HZOL can reverse LPS-induced changes relating to the inflammatory cytokines and immune dysfunction and attenuating the expressions of TLR4, CD14, MyD88, NF-κB p65, and p-NF-κB p65 of the TLR4/NF-κB p65 pathway." (PMID 36845637, 2023). "This process of immune dysfunction following traumatic injury is dominated by the pattern recognition receptors TLR2, TLR4 and TLR9." (PMID 37108280, 2023). "However, the alleviation of immune disorders by knocking down TLR2 or TLR4 alone remained unimpressive due to the HMGB1 preferential recognition effect of TLR2 and the compensation effect of TLR4." (PMID 36139393, 2022). "Our data demonstrate that direct engagement of TLR4, expressed on the cell surface and localized in the early endosome, enhances IFN-γ production and reduces IL-4 production by iNKT cells, which modulates immune responses in various iNKT cell-mediated immune diseases." (PMID 23028952, 2012). "To investigate whether TLR4-mediated differential production of IL-4 and IFN-γ by iNKT cells regulates iNKT cell-mediated immune diseases, we compared joint inflammation in CD1d−/− mice adoptively transferred with either WT or TLR4-deficient iNKT cells in the K/BxN serum transfer model." (PMID 23028952, 2012). "TLR4, TLR7, and TLR21 expression levels in G1 broilers without cold stimulation training were considerably down-regulated after ACS, indicating that ACS leads to immune dysfunction in broilers." (PMID 36496781, 2022).
kidney (42 papers, 2006 to 2025). "For example, PELI1 activates the PI3 K/Akt/GSK3β signaling pathway, leading to poor prognosis of patients, and PELI3 promotes colorectal carcinogenesis through TLR4-mediated inflammation." (PMID 40500708, 2025). "Mechanistically, the activation of Dectin-1 led to the downregulation of TLR4 and its co-receptor CD14, thereby, undermining the TLR4 signaling in hepatic stellate cells and inhibiting liver fibrosis and oncogenesis." (PMID 39590166, 2024). "Studies have shown that there is an upregulation of TLR4 in CKD and activation of TLR4 by LPS triggers a pro-inflammatory response that contributes to the development and progression of kidney pathologies." (PMID 38732038, 2024). "Adoptive transfer of AKT- or MST1-overexpressing macrophages, or Keap1 disruption in myeloid-specific TSC1-knockout mice promoted NRF2 activation but reduced TLR4 activity and mitigated I/R-induced liver inflammation." (PMID 38360839, 2024). "The results indicate that B. lactis SF can protect the intestinal barrier function by regulating the structure of intestinal flora, thus inhibiting TLR4/NF-κB signaling and the secretion of inflammatory cytokines and alleviating liver injury." (PMID 36986084, 2023). "A recent report implicated RP105 in preventing renal ischemic and septic acute kidney injury mediated by TLR4 signaling pathways." (PMID 36136452, 2022). "The present findings suggest that I-postC can reduce tissue injury and kidney inflammation induced by limb I/R injury, possibly via inhibition of the TLR4 and NF-κB pathways." (PMID 34210334, 2021). "First, our results lacked sufficient statistical power to assess the exact roles of TLR-4 SNPs, mRNA and protein expression in colorectal carcinogenesis due to relatively small sample sizes." (PMID 24705379, 2014). "The potential regeneration signaling patterns of TLR4 in acute kidney injury, are also discussed." (PMID 36674930, 2023). "Indeed, the interaction between LPS and toll-like receptor 4 (TLR4) is crucial in the initiation and promotion of hepatocarcinogenesis through inflammation, chronic liver injury and fibrosis." (PMID 34204274, 2021). "Furthermore, these protective effects of RIPC against liver IR injury appear to be mediated by KATP through inhibiting HMGB1-induced TLR4/MyD88/NF-κB signaling." (PMID 31771292, 2019). "Consequently, we performed the present meta-analysis to evaluate the exact role of TLR-4 in colorectal carcinogenesis." (PMID 24705379, 2014). "Five studies evaluated the potential role of TLR-4 mRNA expression in colorectal carcinogenesis." (PMID 24705379, 2014). "In our present study, we found that pigs with M. hyorhinis infection had evidence of lung inflammation, including significant interstitial infiltration of inflammatory cells and thickening of the alveolar walls, as well as the activation of the TLR4/MyD88/NF-κB p65 signaling pathway." (PMID 35699454, 2022). "Because the ceramide/TLR4/β-catenin axis regulated SOAT1 expression in CRC, the role of SOAT1 in ceramide-mediated colorectal tumorigenesis was investigated by us." (PMID 34914638, 2022). "In kidney injury models, ROS-responsive nanoparticles (RBCM@CeO2/TAK-242) were effective only when combined with anti-inflammatory agents (e.g., TAK-242) that suppress M1 macrophage polarization and TLR4/NF-κB signaling." (PMID 40839685, 2025). "In accordance with results in A549 and H1299 cell lines, TLR4 was highly expressed in murine lung ADC cell line-LLC cells and M3G treatment failed to regulate their viability." (PMID 33628591, 2021). "Evidence has revealed that the absence of TLR4 genes in the liver reduces liver IR injury, and TLR4 blockade affects the function of hepatocytes and Kupffer cells, depresses the production of proinflammatory cytokines (TNF-α and IL-6) and ameliorates hepatocellular IR injury." (PMID 27347929, 2016).
cardiac disease (25 papers, 2012 to 2026). "Further studies showed that SARS-CoV-2 binding to receptor proteins in target cells resulted in reduced ACE2 expression levels (low levels of ACE2 are a risk factor for heart disease) and TLR4 activation is a potential mechanism leading to cardiac diseases, especially myocarditis." (PMID 35749386, 2022). "The effectiveness of TLR4 antagonists and inhibitors has already been demonstrated in animal models of various cardiac diseases." (PMID 38790263, 2024). "As a key regulator of inflammation, toll-like receptor 4 (TLR4) plays an important role in pathogenesis of cardiac diseases." (PMID 28690610, 2017). "The role of TLR4 activation is not only limited to septic cardiomyopathy but also plays a significant role in other cardiac diseases." (PMID 28690610, 2017). "For example, what is the exact role of TLR4 in the pathogenesis of cardiac diseases, pro-inflammatory or anti-inflammatory?" (PMID 27228349, 2016). "In addition, a correlation was suggested between the reduction in TLR4 (Toll-like receptor 4) and the protective effect of exercise in heart diseases." (PMID 38248849, 2024). "Other chemical compounds, such as Triad3A (a ubiquitin E3 ligase), TAK-242, and lipopolysaccharide from Rhodobacter sphaeroides (LPS-RS), have been reported to negatively regulate the NF-κB activation pathway via the inhibition of TLR4/TLR9 or TLR4 and subsequently inhibit cardiac disease." (PMID 37113698, 2023). "While there were no clear differences between male and female animals, additional work in larger cohorts may be required to confirm this result, and to test the inhibition of TLR4 as an intervention strategy in radiation-induced heart disease." (PMID 36672353, 2023). "Further studies are required to understand radiation-induced inflammation in the heart, determine whether sex differences occur, and test whether TLR4 may be a target for intervention in radiation-induced heart disease." (PMID 36672353, 2023). "TLR2 and TLR4 play a central role in the pathogenesis of diverse heart disorders." (PMID 35891270, 2022). "Therefore, further studies focused on the expression of TLR4 and downstream genes in different stages and categories of cardiac disease are needed to confirm these findings." (PMID 35273164, 2022). "This implies that TLR4 inhibition is a potential therapeutic target for lipotoxic heart disease." (PMID 33762947, 2021). "Reducing TLR4 mediated fibrosis and apoptosis could be a novel approach in the treatment of heart diseases, where apoptosis plays an important role." (PMID 33159115, 2020). "For example the TLR4 Asp299Gly SNP has been associated with heart disease in some studies but not others." (PMID 23730203, 2012). "Moreover, despite the extensive knowledge of the role of TLR4 in cardiac disease, its role in radiation-induced heart disease is largely unknown." (PMID 36672353, 2023). "We hypothesized that a low dose of BNZ in combination with a therapeutic vaccine (TSA-1-C4 and Tc24-C4 antigens formulated with a synthetic TLR-4 agonist-adjuvant, E6020-SE) given during early chronic infection, could prevent cardiac disease progression and provide antigen-specific T cell immunity." (PMID 36095001, 2022). "Despite these promising findings, TLR4 inhibitors or antagonists for the prevention or treatment of cardiac diseases have not yet entered human clinical trials." (PMID 38790263, 2024). "In order to evaluate the consequences of systematic pharmacological analysis, we examined the effect of the QX1 formula on key proteins in the integrated “cardiac disease-related pathways,” including calcium, MAPK, PI3K/AKT, and TLR4 signaling pathways using Western blot." (PMID 32908632, 2020). "However, the prevention or treatment of cardiac diseases using TLR4 inhibitors or antagonists has not currently been launched in human clinical trials." (PMID 35273164, 2022).
cardiac disease (continued). "However, the improvement or treatment of cardiac diseases with TLR4 inhibitors to date have not been launched in clinical trials, possibly because TLR4 inhibitors such as TAK-242 and eritoran have shown inadequate efficacy in other systems or organs." (PMID 33324685, 2020). "However, the prevention or treatment of cardiac diseases with TLR4 inhibitors or antagonists to date has not been launched in human clinical trials." (PMID 27228349, 2016).
adenocarcinoma (22 papers, 2010 to 2025). A common cancer characterized by the presence of malignant glandular cells. "The TLR4 9:117713042 variant showed significant association with mucinous histology (23.5% vs 7.4% in conventional adenocarcinomas, p=0.038)." (PMID 40703545, 2025). "Here, we show that TLR4 is downregulated in EC; a finding that corroborates initial studies, where TLR4 was significantly downregulated in endometrial hyperplasia and adenocarcinoma when compared with controls (i.e. postmenopausal women)." (PMID 40871563, 2025). "Adenocarcinoma patients with higher TLR4 expression in the stromal compartment had a significantly increased risk of disease progression and relapsed significantly earlier than those with lower expression levels." (PMID 36647071, 2023). "The conjugated form of Toll-like receptor 4 (TLR4) with AuNPs was used as an adjunct therapy for human adenocarcinoma alveolar basal epithelial cells (A549 cells), which led to the downregulation of the expression of this receptor." (PMID 37538179, 2023). "The TICAM2 physically bridged toll like receptor-4 (TLR4) with TICAM1 and the TLR4 partially regulated by the HIF during adenocarcinoma." (PMID 23122428, 2012). "We found that adenocarcinoma patients (pT1-4) with higher TLR-4 expression in stromal compartment had a significantly increased risk in disease progression." (PMID 21059221, 2010). "Furthermore, participants with pT3 adenocarcinoma with high TLR4 expression (over 50% positive cells) relapsed sooner (14 months) compared to participants with low TLR4 expression (40 months, RR 3.15; log-rank chi-square 4.03, P < 0.05)." (PMID 35841426, 2023). "Receptors, including RAGE, TLR2, and TLR4, may be upregulated in the adenocarcinoma or stroma cells." (PMID 33167343, 2020). "We then asked whether TLR4 expression is increased in the important adenocarcinoma precursor, adenomatous polyps." (PMID 24887394, 2014). "Given the relationship between TLR-4 expression and survival in adenocarcinomas, and the general tendency towards increased inflammatory markers as a function increasing tissue dysplasia up to malignancy, we then investigated several markers of inflammatory cells and angiogenesis." (PMID 21059221, 2010). "Previously, our group assessed the levels of toll-like receptor 4 (TLR4), its co-receptor CD14, and the NF-κB p65 subunit to investigate the role of β-carotene in inhibiting the lipopolysaccharide (LPS)/TLR4 signaling pathway in human adenocarcinoma colon epithelial (HT-29) cells." (PMID 39588046, 2024).
peripheral neuropathy (15 papers, 2016 to 2025). A disorder affecting the peripheral nervous system. "Evidence suggests that TLR4 promotes TRPV1 overexpression in DRG neurons during paclitaxel-induced peripheral neuropathy and inflammation." (PMID 31775332, 2019). "Intrathecal administration of the recombinant AIBP protein reduces TLR4 dimerization and lipid raft levels, the key characteristics of TLR4 inflammarafts, and alleviates tactile allodynia in a mouse model of chemotherapy-induced peripheral neuropathy." (PMID 39342323, 2024). "This TLR4 signaling regulates chemotherapy-induced peripheral neuropathy in mice, and in the current work, cisplatin related chemotherapy-induced loss of motor dysfunction is ameliorated using αvβ3 integrin receptor antagonist to inhibit NF-kB activation and inflammation." (PMID 32174830, 2020). "TLR4/MyD88 has been reported to be involved in paclitaxel-induced peripheral neuropathy in rats." (PMID 31775332, 2019). "Our previous study also found that inhibition of the Notch pathway could reduce the expression of inflammatory factors accompanied by repressive glia response through the HMGB1/TLR4 signalling pathway in a rat model of nab-paclitaxel-induced peripheral neuropathy." (PMID 36819745, 2023). "Moreover, it was found that increased expression of TLR4 in monocytes could be related to systemic inflammation in peripheral neuropathy in T2DM." (PMID 36671424, 2022). "Therefore, TLR4/MyD88 signaling is involved in paclitaxel-induced peripheral neuropathy." (PMID 31775332, 2019). "However, it was recently reported that NETs could trigger the NLRP3 inflammasome activation and IL-18 secretion release during the occurrence of oxaliplatin-induced peripheral neuropathy (OIPN) via the induction of the LPS-toll-like receptor 4 (TLR4)-JNK pathway." (PMID 38188146, 2024). "However, under chronic inflammatory conditions, TLR4 dimers and increased lipid raft levels are surprisingly persistent; they can be found in spinal microglia 21 days after a chemotherapeutic intervention, which results in peripheral neuropathy and a persistent pain state." (PMID 39342323, 2024). "The present study demonstrates the critical role of HMGB1 in the development and maintenance of oxaliplatin-induced peripheral neuropathy, which is mediated by RAGE, TLR4, and CXCR4." (PMID 31666085, 2019). "Toll-like receptors (TLR-1, TLR-2, and TLR-4) and the transient receptor potential family of ion channels (TRPV1 and TRPV4) have been discovered, demonstrating their active role in chemotherapy-induced peripheral neuropathy." (PMID 35956877, 2022). "We next asked whether well-known, pro-nociceptive receptors for HMGB1, such as TLR4, RAGE, and CXCR4, contributed to the oxaliplatin-induced peripheral neuropathy." (PMID 31666085, 2019). "Also, we demonstrated the necessity of TLR4 in both male and female migratory responses similar to other studies showing that TLR4 signaling is critical for CCR2-dependent monocyte migration through binding of MCP1 to CCR2 in LPS studies, in angiogenesis and peripheral neuropathy." (PMID 35422759, 2022). "Furthermore, studies have reported sensitisation of DRG primary sensory neurons in PTX-induced peripheral neuropathy through induction of monocyte chemoattractant protein-1(MCP-1/CCL2) and its receptor CCR2, as well as toll-like receptor 4 (TLR-4) signalling in the DRG via MAP kinases and NFkB." (PMID 28125674, 2017).
liver (13 papers, 2013 to 2024). "Specifically, we found that LPS-induced upregulation of METTL3 and m6A modification in mice led to severe colon inflammation through activation of the TLR4/NF-κB-mediated inflammatory pathway in macrophages." (PMID 38725850, 2024). "Regulatory DCs in Galectin-3:Toll-like receptor-4:Kynurenine-dependent manner promoted the expansion of colon-infiltrated T regulatory cells (Tregs) and suppressed Th1 and Th17 cell-driven colon inflammation." (PMID 31336879, 2019). "Fermented ginseng with probiotics (Lactobacillus fermentum) could relieve AAD symptoms and colon inflammation, decrease the expression of immune elements such as TLR4 and NF-κB in the colon, and restore the gut microbiota to its original state." (PMID 35345778, 2022). "Our results indicated that Gal-3 is required for TLR-4-dependent activation of IDO-1/KYN pathway in colon-infiltrating DCs and for consequent Tregs-based suppression of Th1/Th17 cell-driven colon inflammation." (PMID 31336879, 2019).
intestinal diseases (11 papers, 2012 to 2025). "A few candidate genes, such as Toll-like receptor 4 (TLR4) and myeloid differentiating factor 88 (MyD88), had been identified in our former studies to be associated with intestinal disorders of rabbit." (PMID 30670754, 2019). "Taken together, these studies suggest that interactions of LPS from bacteria and TLR4, resulting in excess proinflammatory cytokines in premature intestinal epithelium, lead to intestinal damage and increase susceptibility of the neonate to intestinal diseases." (PMID 33510368, 2021). "These proteins also play roles in TGF-β and TLR-4 signaling pathways and in intestinal disease pathogenesis." (PMID 25668313, 2015). "Hence, pathogenic C. coli but not commensal E. coli caused differential kinetics in fecal bleeding in IL-10−/− and TLR4−/− IL-10−/− mice, indicating that TLR4 was involved in mediating the pathogen-induced signs of intestinal disease." (PMID 33261211, 2020). "As LPS-TLR-4 signaling, as well as TLR-4 and HSP interactions are crucial elements in intestinal inflammation, our data support the notion that TGF-β2 may protect against intestinal diseases during early life." (PMID 25668313, 2015). "Studies in recent years have found that the expression of TLR4 in the colon and distal ileum epithelium of the patients with IBD is significantly higher than that of normal people, indicating that TLR4 and its signal transduction pathway may play an important role in intestinal diseases." (PMID 31671112, 2019).
respiratory disease (10 papers, 2015 to 2025). "Several studies have demonstrated that TLR4 expression is increased in active respiratory disease and is responsible for proinflammatory cytokine production, in both viral and bacterial induced infections." (PMID 33901263, 2021). "The detailed positive feedback loop between DAMPs and TLR4 and the function of neutrophils' TLR4/TLR3 in respiratory diseases had already been reviewed by other researchers." (PMID 28589151, 2017). "Further in vitro studies showed that both RSV and RSV VLPs were sensed by TLR-4, and both induced a Th1-cytokine but not the Th2 cytokines; only the latter are known to be associated with respiratory disease enhancement." (PMID 26172453, 2015). "Therefore, aesculetin targeting TLR4 and EGFR may find use in treating airborne PM-associated respiratory diseases." (PMID 33809902, 2021). "According to core hub, genes were analyzed by degree methods, we infer that TLR4, SMPDL3B, and NFκBIA may be important regulatory genes in calves' immune response to respiratory disease." (PMID 37180342, 2023). "While expression of IL-6 and TLR-4 was not altered in our study, the pattern of expression suggests that animals that acquired BRD were actively combating respiratory disease agents at arrival and did not possess active molecular pathways necessary for mitigating prolonged inflammation." (PMID 31929561, 2020).